GSPT1 (G1 to S phase transition 1)
Diseases named in the same sentence as GSPT1 in open-access papers (continued):
Sharing a sentence is not in itself a finding about the gene and the disease.
leukemia (4 papers, 2022 to 2025). A malignant (clonal) hematologic disorder, involving hematopoietic stem cells and characterized by the presence of primitive or atypical myeloid or lymphoid cells in the bone marrow and the blood. "Additionally, the degradation of GSPT1 led to a reduction in the levels of these leukemia-causing gene fusions, highlighting the critical role of GSPT1 in the disease." (PMID 39857993, 2025). "Treatment of Mll-Af9 leukemia cells with CC-885 caused effective degradation of Gspt1." (PMID 35763353, 2022). "Thus, we conclude that ETF1 binding and associated GTPase activity are likely to be the key mediators of leukemia cell death following loss of GSPT1." (PMID 35763353, 2022). "While Mll-Af9 leukemias are effectively killed in this model, LT-HSCs are relatively spared, an important finding for the clinical translation of GSPT1-degrading drugs." (PMID 35763353, 2022). "We next sought to assess the effects of GSPT1 degradation on normal stem cells, hematopoiesis, and leukemia cells in vivo." (PMID 35763353, 2022). "Using this model, we were able to demonstrate the efficacy of Gspt1 degraders in a leukemia model while preserving LT-HSCs." (PMID 35763353, 2022). "To understand the mechanistic basis for GSPT1 dependency in leukemia cells, we first sought to define the domains within GSPT1 critical for leukemia cell survival using an unbiased tiled CRISPR depletion screen." (PMID 35763353, 2022). "Nonetheless, GSPT1 plays a central role in mRNA translation, and depletion of GSPT1 activates an integrated stress response that leads to cell death in leukemic cells while sparing normal hematopoietic stem cells and reduces leukemia engraftment and LSCs in primary adult AML patients." (PMID 39857993, 2025). "Leukemia developed from CrbnV380E/I391V mice is sensitive to drugs that degrade Gspt1." (PMID 35763353, 2022). "Therefore, we aimed to create a humanized mouse Crbn for the study of GSPT1 degraders and develop an in vivo model sensitive to both CC-885 and CC-90009 to study the efficacy and toxicity of these molecules for the treatment of leukemia." (PMID 35763353, 2022). "GSPT1 degradation and the resulting impaired translation termination and activation of the ISR pathway represent a novel mechanism of inducing leukemia cell death." (PMID 35763353, 2022). "In concordance with a prior study, we show that GSPT1 degradation leads to activation of the ISR pathway and cytotoxicity in leukemia cells." (PMID 35763353, 2022). "Previous findings showed that depletion of GSPT1 by the molecular glue degrader CC-90009, a cereblon E3 ligase modulating drug that coopts CRL4CRBN to selectively target GSPT1 ubiquitination and proteasomal degradation, rapidly induces AML apoptosis and reduces leukemia engraftment." (PMID 39857993, 2025). "The GSPT1 GTPase and ETF1 binding domains are critical for leukemia cell survival." (PMID 35763353, 2022). "Moreover, GSPT1 interacted with ELAVL1 and EIF4B, proteins associated with favorable AML outcomes, while KPNA1 negatively interacted with PPP1CA, a marker of poor prognosis, suggesting its role in modulating negative prognostic pathways in leukemia." (PMID 39940906, 2025).
lung carcinoma (4 papers, 2021 to 2025). "Notably, the disruption of translation termination through GSPT1 degradation is selectively cytotoxic to MYC-driven lung cancers and lung NECs, including SCLC." (PMID 40551250, 2025). "Overexpression of CRBN in non-NE lung cancer cell lines enhanced GSPT1 degradation kinetics and significantly increased sensitivity to CYRS381." (PMID 40551250, 2025). "Notably, it has been reported that GSPT1 promotes the proliferation, invasion, and migration of NSCLC cells, enhances tumorigenicity, and promotes the progression of lung cancer." (PMID 33819920, 2021).
non-small cell lung carcinoma (3 papers, 2014 to 2025). A group of at least three distinct histological types of lung cancer, including non-small cell squamous cell carcinoma, adenocarcinoma, and large cell carcinoma. "LINC00511 has ben shown to promote proliferation, invasive capacities, and migration of non-small cell lung cancer cells through regulating miR-625-5p/GSPT1 axis." (PMID 37124625, 2023).
viral infections (3 papers, 2024 to 2025). "Collectively, by orchestrating the depletion of GSPT1, compound 103 presents a robust defense against a variety of viral infections in human cells." (PMID 40871554, 2025). "The mechanism of action involves GSPT1 degradation and the modulation of eIF2α, a key component in the cellular response to viral infection." (PMID 40871554, 2025). "The implication that previously reported GSPT1 degraders could be repurposed for treating viral infections opens new avenues for the development of broad-spectrum antiviral therapies, potentially transforming the treatment landscape for multiple viral diseases." (PMID 39500878, 2024).
cancers of the stomach (2 papers, 2014 to 2015). "It has been previously reported that GSPT1 mRNA level is increased in 70% of the intestinal type gastric tumors and strongly decreased during human chondrocyte differentiation." (PMID 25028095, 2014).
glioblastoma (2 papers, 2024 to 2025). The most malignant astrocytic tumor (WHO grade IV). "The present study demonstrated that GSPT1-KO U87 glioblastoma cells and CC-885 treated U87 glioblastoma cells enhanced apoptosis at both cellular and individual levels." (PMID 39117611, 2024). "Next, the relationship between GSPT1 expression and overall survival was examined in patients with glioblastoma." (PMID 39117611, 2024). "Herein, to examine the potency of GSPT1 as a novel target for primary brain tumor treatment, we used CC-885 to treat brain tumors produced by transplantation of U87 glioblastoma cells into the brains of nude mice." (PMID 39117611, 2024). "In the current study, we found that U87 glioblastoma cells demonstrated higher GSPT1 expression than LN229 glioblastoma cells and that U87 cells showed similar expression of GSPT1 as HeLa cells." (PMID 39117611, 2024). "To further confirm the effects of GSPT1 on cell growth and survival of mice, we generated GSPT1-KO U87 glioblastoma cells with stable overexpression of GSPT1-FLAG (hereafter referred to as Rescued GSPT1-KO U87 cells)." (PMID 39117611, 2024). "Taken together, it can be concluded that drugs which decrease GSPT1 protein levels are promising candidates for glioblastoma therapy." (PMID 39117611, 2024). "In conclusion, we demonstrated that GSPT1 is a novel target for the development of therapeutics against glioblastoma." (PMID 39117611, 2024). "To examine the potential of GSPT1 as a therapeutic target for glioblastoma, we evaluated apoptosis in both GSPT1-KO U87 cells and brain tumors produced by transplanted GSPT1-KO U87 cells." (PMID 39117611, 2024). "To confirm the relationship between GSPT1 expression levels and the survival period, we generated GSPT1-KO U87 glioblastoma cells using genome editing." (PMID 39117611, 2024). "GSPT1 expression was confirmed in patients with glioblastoma." (PMID 39117611, 2024). "GSPT1 was expressed in the cytoplasm, similar to U87 glioblastoma cells." (PMID 39117611, 2024). "In the present study, we showed that GSPT1-KO delayed the growth of U87 glioblastoma cells." (PMID 39117611, 2024). "Furthermore, we examined GSPT1 expression levels and the relationship between GSPT1 mRNA levels and patient prognosis using glioblastoma samples from 87 patients." (PMID 39117611, 2024). "We examined the expression levels of GSPT1 in glioblastoma samples." (PMID 39117611, 2024). "Herein, we examined the potential of GSPT1 as a novel target for glioblastoma therapy." (PMID 39117611, 2024). "CC-885, a cereblon modulator that degrades GSPT1 by bridging GSPT1 to the CRL4 E3 ubiquitin ligase complex, was administered to nude mice with transplanted brain tumors of U87 glioblastoma cells." (PMID 39117611, 2024). "GSPT1 mRNA expression levels did not significantly correlate with the overall survival period in patients with glioblastoma." (PMID 39117611, 2024). "Taken together, we propose that GSPT1 is an essential protein for glioblastoma growth, but not its malignant characteristics, and that GSPT1 is a potential target for developing glioblastoma therapeutics." (PMID 39117611, 2024). "GSPT1 may not affect cell growth or malignancy if a certain amount of protein is present in the glioblastoma cells." (PMID 39117611, 2024).
multiple myeloma (2 papers, 2018 to 2022). "UBE2G1 loss also reduced the degradation of GSPT1 induced by CC-885 in myeloma cell lines OPM2, DF15 and MM1S, AML cell lines OCI-AML2, U937, MOLM-13 and MV4-11, as well as 293T human embryonic kidney cells." (PMID 30234487, 2018).
testicular germ cell tumor (2 papers, 2025). A germ cell tumor arising from the testis. "There is a statistically significant relationship between the rs4561483 risk genotype and increased GSPT1 expression in testicular germ cell tumors (TGCTs)." (PMID 39940786, 2025).
alopecia (1 paper, 2022). Hair loss usually from the scalp. "Additionally, GSPT1 was downregulated in androgenetic alopecia patients, possibly associated with alopecia progression." (PMID 36386842, 2022).
brain tumors (1 paper, 2024). "Brain tumors with transplantation of GSPT1-KO U87 cells also showed enhanced apoptosis compared to those with transplantation of WT and Rescued GSPT1-KO U87 cells." (PMID 39117611, 2024). "Therefore, thalidomide derivatives/immunomodulatory drugs with <450 molecular weight, which bind to CRBN and lead to degradation of GSPT1, are potentially effective therapeutics for primary brain tumors." (PMID 39117611, 2024). "However, the effects of GSPT1 depletion/deletion and thalidomide derivatives on primary brain tumors have not yet been reported." (PMID 39117611, 2024).
breast tumor (1 paper, 2008). "To evaluate epigenetic differences in tumor-related genes relating to ER and HER2/neu status of primary tumors, we examined the promoter methylation status of the promoter region CpG islands of eight major breast tumor-related genes (RASSF1A, CCND2, GSPT1, TWIST, APC, NES1, RARβ2, and CDH1)." (PMID 18485221, 2008).
cervical cancer (1 paper, 2020). A primary or metastatic malignant neoplasm involving the cervix. "Methods: lnc-SNHG16, miR-128, GSPT1 and WNT3A expression were analyzed using quantitative real-time PCR and bioinformatics in cervical cancer tissues and cells." (PMID 32127947, 2020).
cervix (1 paper, 2024). "We previously reported that HeLa cells, a cell line derived from cancer of the uterine cervix, demonstrated high GSPT1 expression." (PMID 39117611, 2024).
COVID-19 (1 paper, 2022). A disease caused by infection with severe acute respiratory syndrome coronavirus 2. "COVID-19 is less likely to happen in people with the cytosolic glutathione S-transferase GSPT1 rs1695 allele." (PMID 36818472, 2022).
diffuse large B-cell lymphoma (1 paper, 2025). "As the representative GSPT1/BTK heterobifunctional degrader, GBD‐9 efficiently concurrently degraded GSPT1 acting as an MGD and degraded BTK1 acting as a PROTACs by recruiting CRBN, and displayed high activity in various diffuse large B‐cell lymphoma (DLBCL) and AML cell lines." (PMID 41194439, 2025).
liver cancer (1 paper, 2024). An epithelial or non-epithelial malignant neoplasm that arises from the liver. "Bioinformatics analysis has indicated that GSPT1 mRNA expression is upregulated in liver cancer and that patients with high expression of GSPT1 mRNA have poor prognosis." (PMID 39117611, 2024). "The group proposed that GSPT1 promotes tumor growth and invasion in liver cancer." (PMID 39117611, 2024).
myeloid leukemia (1 paper, 2022). A clonal proliferation of myeloid cells and their precursors in the bone marrow, peripheral blood, and spleen. "To investigate the downstream effects of GSPT1 degradation in an unbiased fashion, we performed RNA-Seq analysis in MOLM13 myeloid leukemia cells treated with CC-885." (PMID 35763353, 2022).
primary effusion lymphoma (1 paper, 2025). A large B-cell lymphoma located in the body cavities, characterized by pleural, peritoneal, and pericardial fluid lymphomatous effusions and that is always associated with human herpes virus-8 (HHV-8). "In addition, the miRNAs‐Target gene analysis of the top 10 regulatory networks on GSPT1 expression by support of PAR‐CLIP methods revealed that other miRNAs (such as miR‐940 in KSHV‐infected primary effusion lymphoma cell lines) may regulate the expression of GSPT1." (PMID 41194439, 2025).
renal carcinoma (1 paper, 2024). A carcinoma arising from the epithelium of the renal parenchyma or the renal pelvis. "Conversely, TCGA datasets of colorectal and renal cancers reportedly showed high GSPT1 mRNA expression and better prognosis." (PMID 39117611, 2024).
Stomach Adenocarcinoma (1 paper, 2025). "Besides, the percentage of GSPT1‐002 expression is increased in ESCA tumors but decreased in Stomach Adenocarcinoma (STAD) tumors compared to normal tissues, but the role of this difference has not been revealed in gastrointestinal cancer." (PMID 41194439, 2025).
cancer (21 papers, 2019 to 2026). A tumor composed of atypical neoplastic, often pleomorphic cells that invade other tissues. "In this study, overexpression of GSPT1 in treated cancer patients was associated with poor survival and low-risk HRs." (PMID 39940786, 2025). "We explored the associations between the abnormal GSPT1 expression patterns and overall survival, disease‐specific survival, disease‐free interval, and progression‐free interval in the Pan‐Cancer Atlas." (PMID 41194439, 2025). "It has also been reported that the overexpression of GSPT1 is related to the specific expression of GGCn alleles in various cancer cells, and that it is a potential oncogene." (PMID 33819920, 2021). "To explicitly clarify the mechanisms underlying the abnormal expression or dysfunction of GSPT1 in cancer, we clarified the upstream regulatory mechanisms, including genomic alterations, transcriptional factors, and microRNA (miRNA), and post‐translational modifications (PTMs)." (PMID 41194439, 2025). "As a result of ubiquitous expression of GSPT1 in both normal and cancer tissues, the GSPT1 MGDs had the problem of a narrow therapeutic window due to systemic degradation, which was summarized as “on target, off cancer toxicity”." (PMID 41194439, 2025). "To date, however, the precise molecular pathways and strategies that confer cancer cell selectivity to GSPT1 MGDs remain largely unexplored, underscoring the need for further research in this area." (PMID 40551250, 2025). "Through single‐cell RNA‐seq analyses in pan‐cancer, we explored the correlation between GSPT1 expression and immune infiltration of immune cells in tumors by evaluating the correlation between GSPT1 with tumor purity, stromal score, and immune score." (PMID 41194439, 2025). "To uncover the potential cancer biology of GSPT1‐mediated oncogenesis, we explored the correlation between GSPT1 expression and the activity of 10 well‐known cancer‐related pathways." (PMID 41194439, 2025). "Understanding the cellular context for the selective targeting of cancer cells by GSPT1 MGDs is crucial." (PMID 40551250, 2025). "In order to understand the cancer biology of GSPT1 in tumors, we first analyzed the structures, distribution, and function of GSPT1 isoforms and described isoform‐specific functions according to the different domains of GSPT1." (PMID 41194439, 2025). "This inherent importance of GSPT1 complicates the development of GSPT1-targeted anti-cancer agents and raises significant concerns about their therapeutic index." (PMID 40551250, 2025). "This review systemically summarizes the structure, expression, regulatory networks, and isoform‐specific signaling of GSPT1 in cancers." (PMID 41194439, 2025). "Cancer cells heavily rely on translation processes to maintain elevated levels of oncoproteins, making GSPT1 an attractive therapeutic target." (PMID 40551250, 2025). "We next analyzed the most potent upstream miRNAs affecting GSPT1 expression in pan‐cancers retrieved from ENCORI (> in 3 tumor types)." (PMID 41194439, 2025). "CRBN expression is a critical determinant of the selective cytotoxicity of GSPT1 MGDs in NECs and other cancers with shared transcriptomic features, such as AML." (PMID 40551250, 2025). "In this review, we focused on the current molecular understanding of GSPT1 expression, regulatory networks, and signaling pathways in cancer biology, and summarized the research progress of GSPT1‐targeted therapies." (PMID 41194439, 2025). "GSPT1, a translation termination factor, has been reported to influence cell cycle regulation and proliferation in cancer." (PMID 41284725, 2025). "Despite these challenges, targeting GSPT1 degradation remains an attractive therapeutic strategy due to its potential to disrupt the production of critical proteins required for cancer cell survival and growth." (PMID 40551250, 2025).